PDK1 (pyruvate dehydrogenase kinase 1)
Diseases named in the same sentence as PDK1 in open-access papers (continued):
Sharing a sentence is not in itself a finding about the gene and the disease.
gastric cancer (35 papers, 2012 to 2026). A primary or metastatic malignant neoplasm involving the stomach. "This is the first study to demonstrate that low-dose DCA treatment provides a minimal effect on cell survival but causes a metabolic shift in gastric cancer cells expressing PDK-1." (PMID 23135628, 2013). "Similarly, our findings regarding PDK1_rs12693006 align with the known roles of PDK1 in cancer-related processes and its association with poor gastric cancer prognosis, suggesting this variant’s involvement in tumor activity." (PMID 39408230, 2024). "DLX6-AS1 is over-expressed in gastric cancer tissues and cell lines, which regulate tumor growth and aerobic glycolysis in gastric cancer by targeting miR-4290 and PDK1." (PMID 34983363, 2022). "The data demonstrate that lncRNA AC093818.1 accelerates gastric cancer metastasis by epigenetically promoting PDK1 expression." (PMID 31988283, 2020). "The score for PDK1 was higher in gastric cancer tissues (n = 55, 45.8%) than the corresponding adjacent tissues." (PMID 31533855, 2019). "We used a Cox proportional hazards regression model to analyze the effects of UFM1 and PDK1 expression and other clinicopathological data on the prognosis of patients with gastric cancer." (PMID 31533855, 2019). "The expression level of UFM1 can improve the poor prognosis of PDK1 in patients with gastric cancer." (PMID 31533855, 2019). "UFM1 suppresses the invasion and metastasis of gastric cancer by increasing the ubiquitination of PDK1 through negatively regulating PI3K/AKT signaling." (PMID 31533855, 2019). "A microRNA-mediated regulation of PDK1 has been described in gastric cancer cells, where miR-128b targets PDK1 thus decreasing cell viability and inhibiting invasion; this effect is achieved through the inactivation of the Akt/NF-κB axis." (PMID 28287465, 2017). "Although we cannot draw direct conclusions that PDK-1 dephosphorylation plays a role in H. pylori-induced gastric cancer, we show that incubation with H. pylori resulted in dephosphorylates PDK-1 protein." (PMID 26487493, 2015). "The results from our immunohistochemical analysis of human gastric cancer tissues demonstrated that the expression of PDK-1, a gate-keeping enzyme that regulates carbohydrate transport into the mitochondria, was significantly correlated with HIF-1α expression." (PMID 23135628, 2013). "As demonstrated by western blotting, PDK-1 was expressed in all of the gastric cancer cell lines as well as the HEK293 cells." (PMID 23135628, 2013). "In conclusion, PDK-1 overexpression in cancer tissues was correlated with poor prognosis in patients with gastric cancer." (PMID 23135628, 2013). "In this study, changes in the use of metabolic processes such as glucose uptake and lactate production in gastric cancer cell lines were dependent on PDK-1 expression." (PMID 23135628, 2013). "The PDK-1 expression level was lower in the AGS cell line in comparison to the other gastric cancer cell lines and the HEK293 cells." (PMID 23135628, 2013). "The expression of c-Myc is remarkably high in gastric cancer, and its binding to the promoter of PDK1 regulates the expression of PDK1, which inhibits PDH activity by phosphorylating PDH, thereby reducing pyruvate conversion into acetyl coenzyme A in the tricarboxylic acid (TCA) cycle." (PMID 41584038, 2026). "Additionally, the effect of UFM1 on gastric cancer cell function is dependent on the expression of PDK1." (PMID 31533855, 2019). "We then investigated whether PDK1 could play a key role in UFM1-mediated gastric cancer metastasis inhibition." (PMID 31533855, 2019). "Hur and his colleagues suggested that the high expression of PDK-1 might act as a biomarker of poor prognosis in gastric cancer patients and PDK-1 inhibitors may be a potential therapeutic target of the patients." (PMID 30988063, 2019). "In addition, we examined the protein level of PDK1 in paraffin-embedded tissue samples from 120 patients with gastric cancer." (PMID 31533855, 2019).
gastric cancer (continued). "Furthermore, we found that the inhibitory effect of UFM1 on gastric cancer cell EMT was also prevented when PDK1 was knocked down." (PMID 31533855, 2019). "Our present results allow us to propose that dephosphorylation of host PDK-1 may represent one of the important mechanisms by which H. pylori induces the development of gastric cancer." (PMID 26487493, 2015). "The percentage of patients who were diagnosed with advanced gastric cancer in our study (72.4%) was higher than that reported in previous studies, which may indicate that PDK-1 can serve as a more specific prognostic marker for more advanced disease stages." (PMID 23135628, 2013). "DCA, an inhibitor of PDK-1, led to metabolic changes in gastric cancer and may therefore serve as an additional treatment option for patients with gastric cancers expressing PDK-1 and for those with a poor prognosis." (PMID 23135628, 2013). "PDK1 has also been identified as a target of miR-375 in esophageal and gastric cancer." (PMID 24137444, 2013). "We have also reported that miR-375 is the most down-regulated miRNA, and that its ectopic expression is able to induce apoptosis of gastric carcinoma cells through downregulation of PDK1 and 14-3-3zeta, implying a tumor-suppressive role of miR-375 in gastric carcinoma cells." (PMID 23442884, 2013). "In addition, PDK-1 inhibitors such as DCA may be considered an additional treatment option for patients with PDK-1-expressing gastric cancers." (PMID 23135628, 2013). "In gastric cancer cells, PPI inhibited the autophagy-regulated PDK1/Akt/mTOR signaling pathway in vivo and in vitro, and induceed cellular autophagy in the gastric cancer cells line HGC-27." (PMID 38324023, 2024). "In gastric carcinoma, PPI treatment facilitates autophagy and induces cell cycle arrest via restraining PDK1/Akt/mTOR signaling pathway in vitro and in vivo." (PMID 38745316, 2024). "Multivariate Cox regression analysis showed that co-expression of UFM1 and PDK1 and TNM stage were both independent predictors for gastric cancer." (PMID 31533855, 2019). "Further studies have shown that UFM1 can inhibit the phosphorylation of AKT and downstream GSK3β by binding to PDK1 and increasing its ubiquitination, thereby inhibiting EMT of gastric cancer cells and exerting a tumor suppressor function." (PMID 31533855, 2019). "Thus, PDK-1 may serve as a biomarker of poor prognosis in patients with gastric cancer." (PMID 23135628, 2013). "Of the gastric cancer cell lines, the glucose uptake and lactate production levels were significantly higher in the MKN45 cell line, which expressed a higher PDK-1 level in comparison to the AGS cell line, which expressed a lower level of PDK-1 (p<0.001)." (PMID 23135628, 2013). "For example, by targeting pyruvate dehydrogenase kinase 1 (PDK1), the PI3K/AKT/mTOR signaling pathway can be effectively inhibited, thereby inducing mitochondria-dependent apoptotic mechanisms and providing a new strategy for gastric cancer treatment." (PMID 38654380, 2024). "Interestingly, PDK1 abundance is controlled by the ubiquitin-fold modifier 1 (UFM1), a member of the ubiquitin-like protein (UBL) family, in gastric cancer cells, leading to PDK1 degradation." (PMID 35269443, 2022). "In addition, as a competitive endogenous RNA in gastric cancer, the lncRNA TINCR has been demonstrated to influence the expression of PDK1 through miR-375, hence influencing gastric cancer cell proliferation and invasion." (PMID 36157234, 2022). "In summary, our study shows that UFM1 may downregulate the expression level of PDK1, which inhibit the AKT/GSK3β pathway and downregulating the EMT activity of gastric cancer cells, leading to suppress the invasion and metastasis of gastric cancer cells." (PMID 31533855, 2019).
gastric cancer (continued). "Immunohistochemistry was performed on gastric cancer tissues obtained from 152 patients who underwent curative resection to assess the expression of hypoxia-inducible factor-1α (HIF-1α), glucose transporter-1 (GLUT-1), hexokinase-2 (HK-2) and PDK-1." (PMID 23135628, 2013). "In this study, we evaluated the therapeutic effects resulting from treatment with DCA, a PDK-1 inhibitor, and the synergic effects of DCA and 5-FU treatment in a gastric cancer cell line expressing a high level of PDK-1 and producing a high level of glycolytic products." (PMID 23135628, 2013). "Similarly, gastric cancer cells acquire a glycolysis-dependent phenotype by upregulating the expression of glycolytic enzymes, including Hexokinase (HK) 1, HK2, Hexokinase Domain Containing (HKDC1), and Pyruvate Dehydrogenase Kinase 1 (PDK1)." (PMID 38273337, 2024). "However, correlations between the expression of other enzymes, such as HK-2 and PDK-1, and gastric cancer prognosis have not been previously reported." (PMID 23135628, 2013).
glioma (35 papers, 2015 to 2026). A benign or malignant brain and spinal cord tumor that arises from glial cells (astrocytes, oligodendrocytes, ependymal cells). "In summary, our findings collectively demonstrate that ATAD2 promotes malignant progression in glioma and synergistically up-regulates PDK1 expression in cooperation with E2F1." (PMID 41158756, 2026). "Previous evidence suggests that JMJD2A demethylates H3K9 and H3K36, thereby activating PDK1 expression and subsequently stimulating the Akt-mTOR pathway to promote glioma growth." (PMID 41011214, 2025). "This dual action further reinforces PDK1 downregulation, amplifies the overall pathway inhibition, and creates a well-coordinated feedback mechanism, thereby restraining glioma cell proliferation." (PMID 41011214, 2025). "But in glioma, when cells are stimulated by driving factors such as K‐Ras, B‐Raf mutations, PGK1 can activate pyruvate dehydrogenase kinase 1 (PDHK1) phosphorylation, suppressing the tricarboxylic acid (TCA) cycle ultimately promoting tumour growth." (PMID 40534132, 2025). "IsocuB was found to inhibit glioma growth by suppressing PDK1, Bcl-2, PI3K-AKT, and MAPK signaling pathways, as well as the activation of MMP-2/9." (PMID 38835342, 2024). "MiR-128-3p targets PDK1, leading to decreased glycolysis levels and dysfunction of mitochondria in glioma cells." (PMID 39272133, 2024). "For example, the splice switch of MYO1B directly regulated by SRSF1 increased the carcinogenic potential of glioma cells through the PDK1/AKT and PAK/LIMK pathways." (PMID 37667311, 2023). "This work showed that circ_0000418 was up-regulated in glioma tissues and cells, and circ_0000418 facilitated the growth and cell cycle progression of glioma cells by decoying miR-409-3p and up-regulating PDK1." (PMID 35264067, 2022). "Circ_0000418 facilitated glioma cell growth, and accelerated the cell cycle by targeting the miR-409-3p/PDK1 axis, indicating that circ_0000418 may be a potential diagnostic marker and a new therapeutic target for glioma, which provides a theoretical basis for the clinical therapy of glioma." (PMID 35264067, 2022). "Pyruvate dehydrogenase kinase 1 (PDK1) belongs to the serine/threonine protein kinase family; PDK1 is significantly overexpressed in glioma tissues, and the knockdown of PDK1 restrains the colony formation ability of glioma cells." (PMID 35264067, 2022). "In this work, we supposed that there was a ceRNA regulatory mechanism among circ_0000418, miR-409-3p and PDK1 in glioma progression." (PMID 35264067, 2022). "Another study reports that PDK1 expression is up-regulated in glioma tissues and cells; silencing of PDK1 expression led to reduced level of lactate and ATP, accumulation of ROS, mitochondrial damage, reduced cell growth, and cell apoptosis." (PMID 35264067, 2022). "In summary, circ_0000418 enhances glioma cell growth and accelerates cell cycle progression by regulating miR-409-3p/PDK1 axis." (PMID 35264067, 2022). "Another study on gliomas indicated that temozolomide resistance results from PDK1- and CHK1-induced modulation of CSCs." (PMID 34768921, 2021). "Taken together, these findings demonstrated that JMJD2A epigenetically regulated the expression of PDK1 to activate Akt-mTOR signaling and promote glioma cell proliferation." (PMID 32256210, 2020). "Further mechanism study implicated that JMJD2A activated the Akt-mTOR pathway and promoted protein synthesis in glioma cells via promoting phosphoinositide-dependent kinase-1 (PDK1) expression." (PMID 32256210, 2020). "Instead, our data revealed that JMJD2A bound at the promoter region of the PDK1 gene to modulate the enrichment of H3K9me3 to promote the expression of the PDK1 gene in glioma cells." (PMID 32256210, 2020). "JMJD2A activated Akt-mTOR signaling pathway and regulated protein synthesis in glioma cells via promoting PDK1 expression." (PMID 32256210, 2020).
glioma (continued). "A series of studies showed that amplified expression of PDK1 was frequently observed in solid tumors and hematological malignancies, such as ovarian cancer, head and neck cancer, glioma, melanoma, and acute myeloid leukemia." (PMID 31506552, 2019). "Our data showed that SOX9 and PDK1 exhibited the similar function in glioma colony formation and sphere formation." (PMID 29416606, 2018). "PDK1 inactivation greatly inhibited glioma cell colony and sphere formation and sensitized glioma spheres to temozolomide (TMZ) toxicity." (PMID 29416606, 2018). "Given the strong effect of DCA on down-regulating EGFRvIII/EGFRvIIIR/PDK1 on glioma cell lines, we investigated its effect in the mouse xenografts." (PMID 28410193, 2017). "In IDH1WT glioma, we observed higher expression of regulator genes PDK1 and PDK3 as compared to IDH1MUT glioma." (PMID 28467784, 2017). "We evaluated the expression levels of E2F1 and PDK1 using 126 surgical glioma specimens." (PMID 41158756, 2026). "However, the interplay between ATAD2 and E2F1 in regulating PDK1 expression in glioma is not yet fully understood." (PMID 41158756, 2026). "Therefore, targeting PDK1 with miR-128-3p represents a potential therapeutic approach for glioma treatment." (PMID 39272133, 2024). "Additionally, qRT-PCR and Western blot experiments were conducted to measure the expression of circ_0000418, microRNA-409-3p (miR-409-3p) and pyruvate dehydrogenase kinase 1 (PDK1) in glioma tissues/cells." (PMID 35264067, 2022). "Additionally, PDK1 is validated to be a target gene of miR-454 in glioma, and miR-454 overexpression significantly inhibits PDK1 expression, thereby suppressing cell growth and blocking the cell cycle in G0/G1 phase." (PMID 35264067, 2022). "In the research, we found that circ_0000418 could decoy miR-409-3p to up-regulate PDK1 expression, which provides a novel explanation of PDK1 dysregulation in glioma cells." (PMID 35264067, 2022). "A previous study identifies PDK1 as a downstream target of miR-128-3p in glioma cells." (PMID 35264067, 2022). "miR-128-3p/PDK1 axis was important in tumor cell metabolism and proliferation in glioma cells." (PMID 36793341, 2022). "Notably, PDK1 promotes glioma cell migration and invasion in vitro and glioma xenograft growth in vivo through up-regulation of c-Jun protein and induction of epithelial-mesenchymal transition." (PMID 35264067, 2022). "By inactivating PDK1, glioma cell colony and sphere formation could be greatly inhibited, and glioma spheres would become more sensitized to temozolomide (TMZ) toxicity." (PMID 35800363, 2022). "PDK1 acted as a target gene of miR-409-3p, and PDK1 could be positively and indirectly modulated by circ_0000418 in glioma cells." (PMID 35264067, 2022). "A previous study reported that glioma cells with IDH1 mutation produce 2-hydroxyglutarate, which promotes HIF-1α degradation, accompanied by the downregulation of glycolysis-related genes including SLC2A1, PDK1, LDHA, and SLC16A3." (PMID 33627136, 2021). "In addition, loss-of-function and gain-of-function experiments showed that JMJD2A promoted PDK1 expression in glioma cells." (PMID 32256210, 2020). "Indeed, we observed that JMJD2A expression was positively correlated with PDK1 expression in glioma tissues." (PMID 32256210, 2020). "Finally, we provided evidence that inhibition of PDK1 with OSU-03012 reduced glioma cell proliferation and blocked the effects of JMJD2A overexpression." (PMID 32256210, 2020). "Inactivation of PDK1 greatly inhibited glioma cell sphere formation." (PMID 29416606, 2018). "While the PDK1 activator PS48 didn’t reveal effect to glioma cell colony formation." (PMID 29416606, 2018). "However, whether circ_0000418/miR-409-3p/PDK1 forms a ceRNA network in the tumorigenesis of glioma needs to be verified." (PMID 35264067, 2022). "In addition, PDK1 inactivation greatly sensitized glioma sphere to temozolomide." (PMID 29416606, 2018).
glioma (continued). "Our data show that Methylstat markedly decreases the mRNA expression levels of PDK1, AKT, and mTOR in glioma cells, contributing to the suppression of the entire AKT/mTOR signaling cascade." (PMID 41011214, 2025). "In line with our findings, previous studies have shown that SRSF1 was increased in gliomas, which promoted gliomagenesis via guided alternative splicing of the MYO1B gene, leading to activation of PDK1/AKT and PAK/LIMK signaling pathways." (PMID 37063420, 2023). "PDK1 and AurA kinase inhibitors, MP7 and alisertib, respectively, acted synergistically in targeting glioma stem cells, inducing their differentiation and apoptosis." (PMID 34768921, 2021). "HIF1α activates target gene expression involved in vascularization, glucose transport, energy metabolism, and growth and metastasis, including VEGF, PDK1, Cyclin-D2, and CA9, and makes glioma cells adapt to hypoxic environments." (PMID 30082910, 2019). "Similar results were observed in glioma tissue samples, the expression levels of TCRP1 has a positive correlation with p-PDK1 (r values=0.5729), or p-AKT1 (r values=0.7802), respectively." (PMID 28436990, 2017). "We selected seven glycolytic genes (HK2, PFKP, ALDOA, PGAM1, ENO1, ENO2 and PDK1) and confirmed their strong up-regulation under hypoxia by QPCR in seven GBM cell lines (five patient derived glioma stem-like cells and two adherent GBM cell lines)." (PMID 25932951, 2015). "Under short‐term treatment conditions compared to vehicle‐treated control cells, glioma cells exhibited minimal or no change in PDK1, PDK2, PDK3, and PDK4 protein expression." (PMID 34058053, 2022). "In a panel of 11 glioma cell lines, IngC acted as a potent inhibitor of protein kinase C (PKC) activity by PDK1 inhibiting and consequently tumor invasion and migration impairment through Wnt/β-catenin (β-C) pathways by lower concentration the effector protein β-C." (PMID 35300350, 2021). "As thus, H3K9me3 and H3K39me3 may share some regions at PDK1 gene locus and JMJD2A targets H3K9me3 to promote the expression of PDK1 in glioma cells." (PMID 32256210, 2020). "In glioma cells, overexpression of c-Myc, a WNT target gene, promotes the Warburg effect via activation of downstream genes, such as glucose transporter (Glut), hexokinase (HK), pyruvate dehydrogenase kinase 1 (PDK1), and lactate dehydrogenase A (LDH-A)." (PMID 28620312, 2017).